Y_RNA (Y RNA )
Gene: Miscellaneous RNA gene on chromosome 9 (127,832,635 to 127,832,743, reverse strand). Ensembl gene ENSG00000222421.
Homologues: Orthologues: chimpanzee Y_RNA (58% identical). Paralogues in human: Y_RNA (75% identical), Y_RNA (74% identical), Y_RNA (73% identical), RNY3 (72% identical), RNY3P14 (72% identical), Y_RNA (72% identical), RNY3P11 (72% identical), RNY3P16 (72% identical), RNY3P1 (71% identical), Y_RNA (71% identical), RNY3P4 (70% identical), RNY3P9 (70% identical), and 86 more.